IGF1R (insulin like growth factor 1 receptor)
Diseases named in the same sentence as IGF1R in open-access papers (continued):
Sharing a sentence is not in itself a finding about the gene and the disease.
tumor (continued). "They found that miR-195 could bind to IGF-1R directly and has a tumor suppressive effect, which was attenuated by IGF-1R expression." (PMID 25628647, 2014). "For the IGF-1R is essentially expressed by most organs and tissues, therefore anti-IGF-1R antibody such as LMAb1 might have side-effects, which may influence the survival rate of mice as well as the anti-tumor effects." (PMID 25424625, 2014). "The question of how IGF-1R becomes overexpressed remains unknown, but accumulating evidence reveals that miRNAs are major regulators of tumor development and progression." (PMID 24810113, 2014). "Conversely, when IGF-1R function was blocked by various strategies, tumor cells undergo apoptosis." (PMID 24961901, 2014). "Tumor response to treatment with anti-IGF1R antibody in the xenograft models was not clearly associated with total IGF1R mRNA expression." (PMID 25170759, 2014). "Considering the multiple inhibitory function of miR-100 on both IGF-1R and mTOR, we speculate that miR-100 may have more potent anti-tumor activity than mTOR inhibitors alone." (PMID 25026290, 2014). "It seems that whether miR-145 can target IGF1R to regulate cell growth is dependent on the cell and tumor types." (PMID 25474488, 2014). "Metformin combined with IGF-1R axis inhibitors may act synergistically to kill tumor cells, as metformin was shown to delay and prevent IGF-1R feedback." (PMID 25289085, 2014). "Upon ectopic expression, PTB-U-box enhances IGF-1R/IR ubiquitination and degradation, thereby inhibiting several key cancer hallmarks, i.e., proliferation, invasion, drug insensitivity and glucose metabolism, and thus retarding the tumor growth in xenograft." (PMID 24970814, 2014). "For example, miR-99a,which was found to be significantly decreased in HCC, could directly targetinsulin-like growth factor 1 receptor (IGF-1R) and mTOR, suggesting that miR-99a is apromising tumor suppressor for HCC." (PMID 25012758, 2014). "The tumor locations and TNM stage were associated with plasma IGF-1R levels." (PMID 24667580, 2014). "Latest studies have suggested that overexpression of IGF1R in the blood of LSCC patients may serve as an independent indicator for tumor recurrence and poor prognosis." (PMID 25184138, 2014). "Downregulation of this lncRNA, as observed in high-risk hematopoietic malignancies, may relax the ‘transcription competition’ control and thus activate the IGF1R gene, leading to growth advantage and tumor progression." (PMID 25092925, 2014). "Phosphorylated IGF-1R was detectable in a minority of the IGF-1R positive tumor cells." (PMID 24489919, 2014). "Overexpression of insulin-like growth factor receptor type 1 (IGF-1R) may promote tumor development and progression in some cancer patients." (PMID 24905030, 2014). "In addition to IGF1R antibodies, a series of low molecular weight TKIs have demonstrated tumor growth inhibitory properties in experimental models." (PMID 24904527, 2014). "IGF and IGF1R expression levels are relevant indicators of tumor stage and/or disease progression." (PMID 25095896, 2014). "A fourth patient (Case # 4), whose tumor demonstrated a MET mutation did not receive IGF1R inhibitor therapy." (PMID 25119929, 2014). "In addition, miR-486 was shown to have a potent tumor suppressor role in NSCLC through direct targeting of IGF-1R as well as IGF-1." (PMID 25628647, 2014). "Nevertheless, the findings of ours and others highlight that miR-143/145 may act as tumor-suppressive miRNAs, and that the targeting of IGF1R may be one mechanism by which the miR-143/145 cluster exerts its tumor suppressive function." (PMID 25474488, 2014). "We assessed IGF-1R in ten tumor samples by ELISA, using NWTb3 cell lysate as a standard." (PMID 23431249, 2013). "In the present study we have determined whether signalling through the IR supports NSCLC tumour cell proliferation when the IGF1R is inhibited." (PMID 23826179, 2013).
tumor (continued). "IGF-1R/IR is an RTK that is known to play an essential role in embryonal tumor cell biology." (PMID 24349301, 2013). "Besides, overexpression and hyperphosphorylation of the IGF-1R in primary breast tumors were reported to correlate with radioresistance and tumor recurrence." (PMID 23663564, 2013). "Their expression and activity may be, at least in some tumor types, even more relevant than that of IGF1R homodimers." (PMID 23383308, 2013). "Moreover, the anti-apoptotic activity of IGF-1R appears to be dispensable for the induction of radiation resistance in a variety of tumor cells suggesting the possibility of an unidentified mechanism." (PMID 24205274, 2013). "In addition, tumor cells derived from IGF-1R+ BC0145 cells or IGF-1Rhi BC0244 cells displayed phenotypic diversity in IGF-1R expression as the original tumor." (PMID 23663564, 2013). "Furthermore, we identified IGF1R as a target gene of miR-140 and confirmed that miR-140 exerts its effect on the inhibition of tumor growth and metastasis by downregulating IGF1R." (PMID 24039995, 2013). "The present findings suggest that the IGF1R signaling system might be correlated with tumor aggressiveness in PDAC, as has been previously reported." (PMID 23962053, 2013). "However, blocking mTOR activity with rapamycin (the prototype mTOR inhibitor) or rapamycin analogs inadvertently activates the Akt-signaling pathway through an IGF-1R-dependent mechanism, which mitigates the anti-tumor effects of the mTOR inhibitors." (PMID 23548153, 2013). "These HRs may also be overexpressed in various tumor cells and specimens as a result of both IGF1R and IR overexpression." (PMID 22438913, 2012). "Blocking of IGF-1R may inhibit tumorigenesis, induce apoptosis and inhibit tumor invasion and metastasis." (PMID 22792362, 2012). "The IGF1-mediated activation of IGF1R has been demonstrated to contribute to tumor progression." (PMID 22792137, 2012). "Additionally, qRT-PCR analysis indicated 13.17- and 2,28-fold up-regulation of IGF1 and its receptor (IGF1R) respectively in tumor tissues." (PMID 23285163, 2012). "Combination analysis was performed grouping MVP and IGF-1R expression in tumours." (PMID 22931894, 2012). "As for their receptors, IGF1R expression enhanced 3.28-fold in tumor tissues." (PMID 23285163, 2012). "In our opinion, combined MVP/IGF-1R expression could be of relevance in predicting the clinical outcome in this tumour type." (PMID 22931894, 2012). "This compound can halt tumor progression by blocking STAT5b and IGF-1R." (PMID 22485142, 2012). "In addition, αIR3 antibody, an IGF-1 mimetic, also induced IGF-1R down-regulation due to receptor internalization, which has been previously observed in tumor cells." (PMID 22879999, 2012). "The present results could help to understand the biological behavior of this tumor type according to the expression not only of IGF-1R, but also of MVP." (PMID 22931894, 2012). "In contrast, there was apparent upregulation of these analytes in the specimen from the IGF1R-resistant tumor that emerged during IGF1R antibody therapy, with predominant nuclear expression of both p-mTOR (Ser2448) and p-Akt (Ser473), consistent with mTORC2 pathway activation." (PMID 21494688, 2011). "The total disease burden and tumor burden of the Igf1r+/− and WT mice were also measured because previous studies show that disease burden is significantly reduced in established mouse models of longevity, e.g., dietary restriction, Ames Dwarf mice, and growth hormone receptor knockout mice." (PMID 22132081, 2011). "This led to proposing the notion of addiction to IGF1R in some tumor cells." (PMID 21437217, 2011). "However, it was predictable that IGF1R would be internalized by clathrin-dependent mechanisms, since this mechanism had already been reported for several RTKs, including IGF1R, in other tumor types." (PMID 21611203, 2011).
tumor (continued). "In patient 1, upregulation of p-Akt and p-mTOR in the tumor that relapsed after initial response to IGF1R antibody might explain the resistance that developed, and the subsequent response to combined IGF1R plus mTOR inhibitor therapy." (PMID 21494688, 2011). "IGF-1R induces anti-apoptosis and increases tumor cell mobility." (PMID 21729319, 2011). "Furthermore, the addition of both IGF-1 and IGF-2 to the PLC HCC cell line induced increased cell proliferation in a dose dependent manner, showing that the major tumor promoting effects of IGF ligands on HCC are exerted through IGF-1R." (PMID 21729319, 2011). "In summary, our findings in vitro strongly suggest L.obtusiloba extract as a specific compound to suppress tumor cell growth and migration and to induce apoptosis in aggressive, poorly differentiated human tumor cells via attenuation of NF-κB transcriptional activity and IGF-1R signaling." (PMID 21569410, 2011). "In the present study, miR-223 suppressed IGF-1R and its signaling and acted as a tumor suppressor." (PMID 22073238, 2011). "Recalling that EGF was downregulated and IGF-2 was strongly upregulated in tumor cells, the level of IGF-1R dysregulation may represent a switch that marks the onset of malignant transformation." (PMID 21464922, 2011). "In this context, our finding of upregulated p-Akt (Ser473) and p-mTOR (Ser2448) in patient 1's resistant tumor that emerged following IGF1R antibody therapy is consistent with a resistance mechanism that could be related to upregulation of TORC2." (PMID 21494688, 2011). "They confirmed the expression of IGF1R by analysing circulating tumour cells." (PMID 20924377, 2010). "Fewer RCC tumor samples (81; 54%) expressed detectable IGF1R mRNA." (PMID 21318160, 2010). "Next, we studied whether AVE-1642-conjugated Alexa 680 targeting to tumours was dependent on IGF1R expression." (PMID 19491901, 2009). "Athymic mice, 4–5 weeks old, were injected with R-/IGF1R cells to form xenograft tumours." (PMID 19491901, 2009). "Therefore, it is necessary to develop non-invasive in vivo imaging technology to quantitatively measure IGF1R levels in metastasised tumours and to be able to track the pharmacodynamic activity of antibody therapy." (PMID 19491901, 2009). "In contrast, only Alexa 680 fluorescence in tumour was dependent on IGF1R expression." (PMID 19491901, 2009). "However, through direct comparison, our data have shown that small-molecule fluorophores, conjugated with monoclonal antibodies, are more suitable to detect IGF1R-expressing tumours in vivo through non-invasive fluorescent imaging." (PMID 19491901, 2009). "Therefore, our data suggest that AVE-1642-conjugated Alexa 680 can identify IGF1R expression and its downregulation in tumour xenograft models." (PMID 19491901, 2009). "Growth factor receptors including EGFR and IGF1R are often overexpressed in tumor cells." (PMID 19323821, 2009). "In addition, previous studies in our lab have shown that AVE-1642 targeted to tumour and downregulate IGF1R levels in tumour after intraperitoneal injection." (PMID 19491901, 2009). "Recently, we demonstrated that the cyclolignan PPP inhibited phosphorylation of IGF-1R without interfering with insulin receptor activity, as well as it reduced phosphorylated Akt, caused apoptosis and induced tumour regression in xenografted mice." (PMID 15956962, 2005). "Furthermore, inhibition of IR and/or IGF1R reduced tumor formation in PTEN-deficient livers but did not completely prevent the appearance of cancerous foci." (PMID 40115165, 2025).
tumor (continued). "The result of the multivariate logistic regression demonstrated a predictive role for IGF1R plasma membrane localisation in determining a Ki67 index higher than 10, emphasizing that the localisation of IGF1R on the plasma membrane is more important for tumour progression than its overall expression." (PMID 40038716, 2025). "Notably, the first clinical trial combining the anti-IGF-1R mAb, cixutumumab, with the mTOR inhibitor, temsirolimus, demonstrated tumor regression of more than 20% in approximately 29% of the patients and a sevenfold increase in median response duration (>14 months) in patients with ES." (PMID 41347090, 2025). "IGF1R has been extensively studied in the context of cancer, where increased IGF‐1R activity is believed to promote the proliferation, migration, and invasion of cancer cells and is associated with tumor metastasis, treatment resistance, and reduced survival rates." (PMID 40152081, 2025). "Therefore, GHR expression, along with IGF1 and IGF1R levels, may provide a more comprehensive understanding of GH signaling in tumor progression." (PMID 40806252, 2025). "Immunohistochemical evaluation of IGF1R phosphorylation and PTPN9 expression in baseline tumor biopsies may serve as a valuable tool to stratify patients who are most likely to benefit from IGF1R-directed combination therapies, thereby facilitating biomarker-driven clinical trial designs." (PMID 41275311, 2025). "PI3K/Akt in TAMs integrates CSF1R/IGF-1R/TLR inputs to drive mTORC1-linked biosynthesis and secretion of IL-6, TGF-β, and pro-angiogenic factors, which in turn activate survival/DNA-repair pathways in adjacent tumor cells and generate leaky neovasculature that impairs drug delivery." (PMID 41002423, 2025). "In addition, to explore the potential mechanism of Let‐7b‐5p in HCC suppression, tumor tissue sections from each group were immunohistochemically stained for the evaluation of IGF1R and Ki67 expression, which are indicative of cell proliferation and signaling pathway activation, respectively." (PMID 40530890, 2025). "However, IGF1R targeting in cancer has proven to be a consistently ineffective strategy in controlling tumor progression, as shown in 183 human clinical trials involving >12,000 patients across several tumor types (2003–2021) at a net cost estimated between $1.6–2.3 billion." (PMID 39000545, 2024). "Thus, while promising effects of IR/IGF-1R inhibition are reported in preclinical studies, combining IR/IGF-1R inhibitors with additional therapeutics in the clinical setting may be necessary to achieve reductions in tumor size." (PMID 38786030, 2024). "Lycopene may also have anti‐tumour effects through other mechanisms than IGF‐1R blockade." (PMID 38515274, 2024). "Therefore, the pro-tumor function of IGF1R could be largely mediated by these downstream signaling cascades." (PMID 38420122, 2024). "However, many studies reported that aberrant expression of IGF1R correlates with tumor development." (PMID 39771106, 2024). "Furthermore, overexpression of IR-A in cancer cells confers resistance to monoclonal antibody therapy, such as trastuzumab (an anti-IGF1-R antibody), suggesting that IR expression can serve as a predictive molecular marker for resistance to tumor-targeted therapies." (PMID 38331804, 2024). "However, following the decreases in hydroxymethylation, IGF1R gene expression levels were higher in the progenitor-like cell types, particularly the OPCs, in the tumors than in the progenitor-like cell types of non-tumor tissue." (PMID 36909536, 2023). "Meanwhile, IGF1 and IGF1R can induce cell proliferation, promote the transcription and expression of vascular endothelial growth factor genes, promote angiogenesis, provide more nutrients for tumor growth, and promote the further development of CRC to advanced stages." (PMID 37266156, 2023).
tumor (continued). "In addition, IGF1R was expressed in the primary tissue of the patient from which OCUM13 was derived, suggesting that OCUM‐13 inherited the mimics of the original tumor and that IGF1R inhibitor might be effective for the original patient." (PMID 36324252, 2023). "Our findings mirror recently published results where DNA replication and IGF1R signaling were identified as key dependencies unique to pediatric tumor types, further suggesting that drug targets within these pathways could be useful therapeutic approaches in pediatric cancer." (PMID 37020198, 2023). "An investigation of the IGF-1R levels’ prognostic significance in a small cohort of 19 women with HGSOC found a significant rise in the expression of the IGF-1R transcript following six cycles of neoadjuvant chemotherapy (NACT) compared to chemo-naïve tumour tissues." (PMID 36768291, 2023). "Among seven potential tumor-suppressing miRNAs identified in this study, high expression of miR-100 was associated with better outcomes in women with luminal A tumors treated with adjuvant endocrine therapy and was inversely linked to mRNA expression of PLK1, FOXA1, mTOR, and IGF1R." (PMID 37508580, 2023). "In addition, Dimer PKM2 can also mediate the disruption of NF-κB/miR-148a/152 and promote the expression of vascular endothelial growth factor (VEGF) as well as the activation of insulin like Growth Factor 1 receptor (IGF-IR), thereby promoting tumour angiogenesis." (PMID 37108242, 2023). "Also based on the IGF-1 level and IGF-1R gene expression, the model could predict significantly the tumor grade (P=0.05) and tumor metastasis (P=0.02), respectively." (PMID 36713521, 2022). "Additionally, by using a logistic regression model and based on IGF-1R protein level, the model could predict significantly the tumor grade (P=0.013), metastasis (P=0.028) and tumor recurrence (P=0.019)." (PMID 36713521, 2022). "Thus, patients with high expression of IGF-1R are prone to suffer tumor metastasis, and IGF-1R levels could be used to predict the prognosis and survival of UM patients." (PMID 36003786, 2022). "Thus, while we cannot entirely rule out an increase in INSR activation in the IGF1R deficient tumor models, there is not a compensatory increase in expression of the INSR." (PMID 36568144, 2022). "Consequently, forced expression of FOXA1 hampered the efficacy of anti-angiogenesis reagent against A549 xenograft tumor, which could be restored by combinatory treatment with IGF1R inhibitor." (PMID 35974000, 2022). "Moreover, despite the important role of IGF system in the carcinogenesis and progression of CRC, the expression and oncogenic activity of IGF-1R and its ligands may vary according to the anatomic location of the primary tumor and molecular profiles." (PMID 35296101, 2022). "Overall, E2 levels were significantly positively correlated with tumor enrichment in the hallmark estrogen response pathway (red bars) and with the expression of genes demonstrated to be transcriptionally regulated by ER (BCL2, IGF1R, GATA3, PIK3CA) and ligand-dependent ER (ESR1, XBP1, TFF1)." (PMID 36428742, 2022). "To determine the effects of luminal epithelial specific Igf1r gene deletion in Wnt1-driven mammary tumorigenesis, we assessed tumor latency rates in the K8iKOR-Wnt1 mouse line compared to the control Wnt1 line and to our prior tumor latency data on the DN-Wnt1 mouse line." (PMID 36568144, 2022). "However, the correlations of IGF-1 and IGF-1R to prognosis and tumor-infiltrating lymphocytes in different cancers remain unclear." (PMID 34804946, 2021). "Moreover, the relationship between IGF1/IGF1R expression and tumor prognoses, such as TMB, MSI, MMR, and DNMT, which can predict the efficacy of immunotherapy, remains unclear." (PMID 34804946, 2021).